BCHE (butyrylcholinesterase)
Diseases named in the same sentence as BCHE in open-access papers (continued):
Sharing a sentence is not in itself a finding about the gene and the disease.
Alzheimer disease (continued). "Cognitive dysfunction in Alzheimer’s disease results from a complex interplay of various pathological processes, including the dysregulation of key enzymes such as acetylcholinesterase (AChE), butyrylcholinesterase (BuChE), and monoamine oxidase B (MAO-B)." (PMID 39883631, 2025). "Emphasis was placed on BChE inhibition due to its increasing clinical relevance in the later stages of Alzheimer’s disease, where BChE expression is elevated in neurofibrillary tangles and amyloid plaques." (PMID 40871591, 2025). "The link between BChE, metabolic disorders and neurological diseases such as Alzheimer’s disease underscores its potential therapeutic role." (PMID 40116876, 2025). "The inhibitory effect on AChE and BChE further positions MLs as a natural source for treating Alzheimer's disease and similar neurodegenerative disorders." (PMID 40351366, 2025). "The results showed a significant potential of the plant to inhibit BChE, which is an important target for the treatment of Alzheimer's disease." (PMID 40202911, 2025). "From a neurological perspective, inhibition of acetylcholinesterase (AChE) and butyrylcholinesterase (BChE) is considered a relevant target in the management of neurodegenerative conditions such as Alzheimer’s disease." (PMID 41008939, 2025). "Rivastigmine is noted for its dual inhibition of both AChE and butyrylcholinesterase (BChE), which is beneficial, given that butyrylcholinesterase activity tends to increase in the later stages of Alzheimer’s disease, while AChE activity decreases." (PMID 40243991, 2025). "These important enzymes have been linked to a wide range of human diseases, including diabetes for α-amylase, Parkinson’s disease for tyrosinase, and Alzheimer’s disease for AChE and BChE." (PMID 41393958, 2025). "This is particularly relevant for the treatment of Alzheimer's disease, where BChE inhibition can help preserve cholinergic function in the brain, potentially delaying cognitive decline." (PMID 40297407, 2025). "AChE and BChE are two important targets in the treatment of Alzheimer's disease (AD), and α-glucosidase is a carbohydrate-hydrolyzing enzyme with therapeutic importance in diabetes." (PMID 40860056, 2025). "Butyrylcholinesterase (BChE) has emerged as a promising therapeutic target in the treatment of Alzheimer’s disease (AD), particularly in its later stages when acetylcholinesterase (AChE) activity declines." (PMID 41322300, 2025). "Inhibition of AChE and BChE, orthosteric or allosteric, or partial agonism of M1 mAChR are correlated with Alzheimer’s disease (AD) symptoms improvement." (PMID 40143145, 2025). "Butyrylcholinesterase (BChE), plays a critical role in alleviating the symptoms of Alzheimer’s disease (AD) by regulating acetylcholine levels, emerging as an attractive target for AD treatment." (PMID 40430266, 2025). "Studies have shown that the therapeutic strategy of inhibiting BChE activity can effectively improve cognitive function in patients with Alzheimer’s disease (AD)." (PMID 38638318, 2024). "The interest in developing BChE selective inhibitors is based on the fact that BChE inhibitors are suggested as a new approach for the treatment of Alzheimer’s disease." (PMID 39684368, 2024). "Their biological activities were assessed by evaluating their ability to inhibit Alzheimer’s disease-related enzymes acetylcholinesterase and butyrylcholinesterase." (PMID 39339437, 2024). "The plant constituents are important in decreasing the development of Alzheimer's disease by inhibiting BChE and AChE." (PMID 39698089, 2024). "Various natural inhibitors of the AChE, BChE, α-glucosidase, and α-amylase enzymes are useful in managing ailments, especially diabetes and Alzheimer’s disease, and the search for more of such compounds is an important domain in medicinal chemistry." (PMID 38893333, 2024).
Alzheimer disease (continued). "The carbonic anhydrase II (hCA II) enzyme was found to be associated with glaucoma, carbonic anhydrase I (hCA I) with epilepsy, acetylcholinesterase (AChE), and butyrylcholinesterase (BChE) with Alzheimer’s disease, and the α-glycosidase enzyme with diabetes." (PMID 39598187, 2024). "For insight into Alzheimer’s disease, the same research group has recently prepared a class of photoswitchable butyrylcholinesterase (BChE) inhibitors and applied them to Alzheimer’s disease in mouse model." (PMID 39407453, 2024). "The investigation into human butyrylcholinesterase (hBChE) inhibitors as therapeutic agents for Alzheimer's disease (AD) holds significant promise, addressing both symptomatic relief and disease progression." (PMID 38784455, 2024). "Co-targeting GSK3β and BChE in Alzheimer’s disease helps to modify disease progression and enhance cognitive function by addressing both tau pathology and cholinergic deficits." (PMID 39204336, 2024). "Cholinesterase enzymes, namely, acetylcholinesterase (AChE) and butyrylcholinesterase (BChE), hold pivotal significance in Alzheimer’s disease (AD) treatment." (PMID 38543134, 2024). "There are two types of cholinesterases, acetylcholinesterase (AChE) and butyrylcholinesterase (BChE), that are attractive as candidate targets for the treatment of Alzheimer’s disease." (PMID 38732642, 2024). "The present research suggests that taxifolin has a strong ability to bind and inhibit AChE and BChE and could be used to manage neuron-associated problems; however, further research is required to explore taxifolin’s neurological therapeutic potential using animal models of Alzheimer’s disease." (PMID 38338420, 2024). "Acetylcholinesterase (AChE) and butyrylcholinesterase (BChE) are vital enzymes involved in the progression of Alzheimer’s disease (AD)." (PMID 39338986, 2024). "AChE and BChE are both well-known enzymatic targets for treatment of Alzheimer’s disease (AD), and AChE and BChE inhibitors (AChEI and BChEI, respectively) have long been of interest." (PMID 38059272, 2024). "Butyrylcholinesterase (BChE) is widely expressed in multiple tissues and has a vital role in several key human disorders, such as Alzheimer’s disease and tumorigenesis." (PMID 38638318, 2024). "Butyrylcholinesterase (BChE) has become a critical target in Alzheimer’s disease (AD) research due to its role in acetylcholine (ACh) hydrolysis and its link to β-amyloid (Aβ) deposition, which worsens disease progression." (PMID 39598703, 2024). "In individuals with Alzheimer’s disease, acetylcholinesterase exhibits a higher prevalence than butyrylcholinesterase within cerebral tissues, playing a pivotal role in the degradation of acetylcholine in the cerebral cortex and hippocampus." (PMID 39596378, 2024). "Behavioral, biochemical, and immunofluorescence analyses showed the efficacy of targeting selectively BChE in Alzheimer's disease." (PMID 38887858, 2024). "In this article, we present the design and synthesis of amino-7,8-dihydro-4H-chromenone derivatives as possible inhibitors of acetylcholinesterase (AChE) and butyrylcholinesterase (BChE) for the management of Alzheimer’s disease (AD)." (PMID 38600537, 2024). "As the tested structures showed drastically better inhibition of the BchE than AchE, these results are very important as BchE has been attracting growing attention due to its positive role in Alzheimer’s disease." (PMID 37175190, 2023). "Leading pathological markers of Alzheimer's disease (AD) include Acetylcholinesterase (AChE), Butyrylcholinesterase (BuChE), Amyloid beta (Aβ) and reactive oxygen species (ROS)." (PMID 37671344, 2023). "Inhibitors of AChE and BChE have found application as drugs developed for the treatment of Alzheimer’s disease which is a neurodegenerative disorder characterized by the loss of memory and consciousness." (PMID 36829813, 2023).
Alzheimer disease (continued). "Among the proteins of therapeutic interest in Alzheimer’s disease and capable of activating a pleiotropic prodrug to form an active ingredient, AChE and butyrylcholinesterase (BuChE) are prime targets." (PMID 37896142, 2023). "The molecular docking of naringenin showed good docking scores against acetylcholinesterase 1E66 and butyrylcholinesterase 6EMI, indicating that naringenin is an intriguing candidate for additional research as a possible medication for Alzheimer’s disease." (PMID 37511887, 2023). "In this research, our approach is to analyze the effect of phytochemicals in Cannabis sativa on multiple culprit enzymes in Alzheimer’s disease, such as AChE (Acetylcholinesterase), BChE (Butyrylcholinesterase), γ-secretase, and BACE-1." (PMID 36771595, 2023). "Selective butyrylcholinesterase inhibitors are considered promising drug candidates for the treatment of Alzheimer’s disease." (PMID 38202655, 2023). "DL controlled Alzheimer’s disease progression through the cholinergic enzymes (AChE and BChE) and the β-amyloid forming enzyme (BACE-1)." (PMID 38066118, 2023). "The multi-targeted profile of cryptolepine, which inhibits both AChE and BChE enzymes, contributes to preventing Alzheimer’s disease." (PMID 36251044, 2023). "The key enzymes involved in Alzheimer’s disease pathways are acetylcholinesterase (AChE) and butyrylcholinesterase (BuChE)." (PMID 37049419, 2023). "The inhibitory activities of the herbal extracts were assessed on the key enzymes that control the occurrence of some NCDs including type II diabetes (T2DM) (α-amylase and α-glucosidase), Alzheimer’s disease (AChE, BChE, and BACE-1) and hypertension (ACE)." (PMID 38066118, 2023). "The main detected compound (naringenin) in the LLEs was docked molecularly with acetylcholinesterase and butyrylcholinesterase as indicators of Alzheimer’s disease development." (PMID 37511887, 2023). "Enzyme butyrylcholinesterase (BChE) shows increased activity in some brain regions after progression of Alzheimer’s disease and is therefore one of the therapeutic targets for symptomatic treatment of this neurodegenerative disorder." (PMID 36769002, 2023). "What’s more, the presence of BChE has been confirmed in amyloid plaques as well as neurofibril tangles, which suggests involvement in Alzheimer’s disease pathophysiology." (PMID 36902286, 2023). "The enhancement of cholinergic functions via acetylcholinesterase (AChE) and butyrylcholinesterase (BuChE) inhibition is considered a valuable therapeutic strategy for the treatment of Alzheimer’s disease." (PMID 36678592, 2023). "Butyrylcholinesterase (BChE) is a major enzyme from the alpha-glycoprotein family that catalyzes the hydrolysis of neurotransmitter acetylcholine (ACh), lowering the concentration of ACh in the nervous system, which could cause aggravation of Alzheimer’s disease (AD)." (PMID 37242249, 2023). "In recent times, research has unveiled their capacity to inhibit acetylcholinesterase (AChE) and/or butyrylcholinesterase (BChE), which are enzymes that play pivotal roles in neurodegenerative disorders such as Alzheimer’s disease." (PMID 37894690, 2023). "For the enzymes involved in Alzheimer’s disease (AChE, BChE, and BACE-1), DL exhibited the highest C score of 0.891." (PMID 38066118, 2023). "It was known that high BChE levels are interconnected with the distinctive neuropathologic characteristic of Alzheimer’s disease (AD) and that both enzymes BChE and AChE are pharmacologically appropriate targets in neurodegenerative disorders." (PMID 37175190, 2023). "Further bolstering its potential application to Alzheimer’s disease (AD) therapy, compound 2 also functioned as an inhibitor of both acetylcholinesterase (AChE) and butyrylcholinesterase (BChE)." (PMID 37892857, 2023).
Alzheimer disease (continued). "Monoamine oxidase-B (MAO-B), acetylcholinesterase (AChE), and butyrylcholinesterase (BChE) have been considered target enzymes of depression and neurodegenerative diseases, including Alzheimer’s disease (AD)." (PMID 36678580, 2023). "The multi-level effect of the raw material has been additionally confirmed by demonstrating that the inhibition of AChE and BChE translates into the nervous system’s response can be used, for example, in the treatment of Alzheimer’s disease." (PMID 35408722, 2022). "In the later stages of Alzheimer’s disease, acetylcholinesterase activity is downregulated by up to 33–45% of normal values, while the activity of butyrylcholinesterase is improved by 40–90% in certain brain regions." (PMID 35630702, 2022). "For prospective benefits in Alzheimer’s disease, a variety of thiazole acetamides were produced and screened for invitro butyryl cholinesterase (BChE) and acetyl cholinesterase (AChE) inhibitory activity (AD)." (PMID 35807236, 2022). "The anticholinesterase activity of seaweed extracts has been tested against acetylcholinesterase (AChE) and butyryl cholinesterase (BChE), which are the main enzymes of Alzheimer’s disease." (PMID 35200670, 2022). "Flavonoids are promising natural products with neuroprotective potential that prevent or slow the progression of Alzheimer disease via the inhibition of key enzymes such as AChE, BChE and BACE-1 (Beta-site APP Cleaving Enzyme-1)." (PMID 36295014, 2022). "Physostigmine holds patents for treating dementia and Alzheimer’s disease as well as inhibiting butyrylcholinesterase, acetylcholinesterase inhibition, and memory enhancement." (PMID 36501282, 2022). "Alzheimer's disease; Butyrylcholinesterase; Liquiritigenin; CoMFA; CoMISA; Molecular docking; Molecular dynamics." (PMID 36544815, 2022). "Butyrylcholinesterase is an acetylcholine-degrading enzyme involved in the memorization process, which is becoming an interesting target for the symptomatic treatment of Alzheimer's disease." (PMID 36544815, 2022). "Acetylcholinesterase (AChE) and/or butyrylcholinesterase (BuChE) inhibitors, such as donepezil, rivastigmine or galantamine, are the only drugs recognized for Alzheimer’s disease (AD) treatment." (PMID 35744919, 2022). "Several compounds were identified as potential acetylcholinesterase (AChE) or butyrylocholinesterase (BChE) inhibitors in the search for potential drug candidates for treating Alzheimer’s disease." (PMID 36297331, 2022). "Current studies have found that butyrylcholinesterase (BuChE) replaces the biological function of acetylcholinesterase (AChE) in the late stage of Alzheimer’s disease." (PMID 35899116, 2022). "The protective effect of Onosma species against Alzheimer’s disease was reported depending on its inhibitory activity on acetylcholinesterase (AChE) and butyrylcholinesterase (BChE) enzymes." (PMID 36557820, 2022). "The essential oil from apricot leaves inhibited acetylcholinesterase as well as butyrylcholinesterase, suggesting its potential for Alzheimer’s disease (AD)." (PMID 35890519, 2022). "Inhibiting AChE and Butyrylcholinesterase (BChE) has developed into a standard method for treating the symptoms of neurodegenerative diseases like Alzheimer’s disease." (PMID 35883492, 2022). "Type-2 diabetes mellitus (T2DM) and Alzheimer’s disease (AD) have shared abnormal levels of the enzymes: acetylcholinesterase (AChE) and butyrylcholinesterase (BuChE)." (PMID 36297317, 2022). "In the late stages of the Alzheimer’s disease, BChE plays a more important role in comparison to AChE." (PMID 36500605, 2022). "Butyrylcholinesterase inhibitors also increase choline levels for the reduction in Alzheimer’s disease symptoms." (PMID 35630702, 2022). "Controversially, it has been demonstrated that zinc carboxylate, evaluated towards acetylcholinesterase (AChE) and butyrylcholinesterase (BChE), displayed high inhibitory activity having a strong potency to block cognitive decline in Alzheimer’s disease." (PMID 36678552, 2022).
Alzheimer disease (continued). "Considering the multifactorial pathogenesis of Alzheimer’s disease, we continuously exploit multifunctional agents that can simultaneously inhibit AChE and BChE and exert antioxidant effects." (PMID 36232533, 2022). "Butyrylcholinesterase activity progressively increases in patients with Alzheimer’s disease, while acetylcholinesterase activity remains unchanged or declines." (PMID 35630702, 2022). "Although no cytotoxic activity was noticed against human colon cancer and human lung cancer, LFD showed 24.04% inhibition against BChE and 60.30% inhibition against AChE and is therefore beneficial for Alzheimer’s disease (AD)." (PMID 36080247, 2022). "As butyrylcholinesterase (BChE) plays a role in the progression of symptoms and pathophysiology of Alzheimer’s disease (AD), selective inhibition of BChE over acetylcholinesterase (AChE) can represent a promising pathway in treating AD." (PMID 36297332, 2022). "AChE and BChE are involved in the pathogenesis of diseases, such as Alzheimer’s disease and type II diabetes mellitus." (PMID 34572429, 2021). "In Alzheimer’s disease (AD), two cholinesterases (ChEs) including acetylcholinesterase (AChE) and butyrylcholinesterase (BChE) are neurotransmitter degrading enzymes, while β-secretase (BACE-1) is involved with β-amyloid formation." (PMID 33924574, 2021). "The ethyl acetate extract showed pronounced inhibitory properties against butyrylcholinesterase, highlighting the possibility for a new, efficient Alzheimer’s disease therapeutic agent." (PMID 34207852, 2021). "Subsequent surveys have determined the relevance of both BChE and AchE in the pathophysiology of Alzheimer’s disease and have demonstrated the therapeutic benefit of the inhibition of both BchE and AchE." (PMID 34679706, 2021). "A number of recent studies have investigated various modifications of sulfonamides, for example, multitarget agents for the inhibition of AChE enzyme, multifunctional agents for Alzheimer’s disease, and/or an in vivo active reversible BChE inhibitor." (PMID 34502357, 2021). "ZnO-NPs also showed excellent inhibitory potential against the enzymes acetylcholinesterase (IC50: 102 μg/mL) and butyrylcholinesterase (IC50: 125 μg/mL) which are involved in Alzheimer's disease." (PMID 34457112, 2021). "These enzymes which are key enzymes were intervening in some human pathologies such as diabetes for α-amylase, neurodegenerative disorders such as Parkinson’s disease for tyrosinase and Alzheimer’s disease for AChE and BChE." (PMID 34579487, 2021). "Emerging of the dual Acetylcholinesterase (AChE)/Butyrylcholinesterase (BuChE) inhibitors has increased for treating Alzheimer disease." (PMID 33869871, 2021). "3-phenylcoumarins bearing aminoalkoxy moiety has been designed to treat Alzheimer’s disease by inhibiting acetylcholinesterase and butyrylcholinesterase." (PMID 34500576, 2021). "The samples were also tested against two important acetylcholinesterase (AChE) and butyrylcholinesterase (BChE) which are among the important drug targets in Alzheimer’s disease." (PMID 34600509, 2021). "AChE and BChE (cholinesterases) enzyme inhibitors are presently being utilized for the treatment/management of Alzheimer’s diseases (AD)." (PMID 34483902, 2021). "Herein, enzymatic inhibitions involving α-amylase and α-glucosidase were investigated for DM type II, acetyl- (AChE) and butyryl-cholinesterase (BChE) for Alzheimer’s disease, and tyrosinase for skin disorders." (PMID 32276531, 2020). "The inhibition of AChE and BChE is considered one of the possible therapeutic strategy against neurodegenerative disorders such as Alzheimer’s disease, senile dementia, and ataxia." (PMID 32825768, 2020). "Both AChE and BChE enzymes are responsible for lowering the level of acetylcholine in the synaptic cleft of the brain leading to neurodegenerative disorders—namely, Alzheimer’s disease, Parkinson disease, and cognitive problems." (PMID 32392806, 2020).